MCCC2 (methylcrotonyl-CoA carboxylase subunit 2)
Description:
Carboxyltransferase subunit of the 3-methylcrotonyl-CoA carboxylase, an enzyme that catalyzes the conversion of 3-methylcrotonyl-CoA to 3-methylglutaconyl-CoA, a critical step for leucine and isovaleric acid catabolism.
Synonyms: MCCB; MCCCβ; MCCCbeta
Tractability: Small molecule: a structure with a bound ligand is known. PROTAC: ubiquitination databases record sites on it; its protein half-life has been measured.
Target class: Enzyme; Ligase
Gene: Protein-coding gene on chromosome 5 (71,579,531 to 71,658,706, forward strand). Ensembl gene ENSG00000131844.
Subcellular location: Mitochondrion matrix
Subcellular location (Human Protein Atlas): Mitochondria
Pathways (Reactome):
Disease: 3-Methylcrotonyl-CoA carboxylase deficiency; Defective HLCS causes multiple carboxylase deficiency
Metabolism: Biotin transport and metabolism; Branched-chain amino acid catabolism
Gene Ontology:
Molecular function: methylcrotonoyl-CoA carboxylase activity; protein binding; ligase activity
Biological process: L-leucine catabolic process; branched-chain amino acid catabolic process; coenzyme A metabolic process
Cellular component: methylcrotonoyl-CoA carboxylase complex; mitochondrial matrix; mitochondrion; cytosol
Genetic constraint (gnomAD): Loss-of-function variants: 47 observed, 72.06 expected, observed/expected ratio (o/e) 0.65, 90% interval 0.51 to 0.83. The upper end of that interval is the gene's LOEUF score, 0.83, which puts it in group 3 of 6, group 1 being the genes least tolerant of losing a copy. Missense variants: 673 observed, 706.43 expected, observed/expected ratio (o/e) 0.95, 90% interval 0.89 to 1.01. Synonymous variants: 248 observed, 247.22 expected, observed/expected ratio (o/e) 1, 90% interval 0.9 to 1.11.
Gene-disease validity (ClinGen):
ClinGen rates the evidence that MCCC2 causes each of these diseases.
3-methylcrotonyl-CoA carboxylase deficiency (autosomal recessive): Definitive.
Homologues: Orthologues: chimpanzee MCCC2 (99% identical), macaque MCCC2 (96% identical), mouse Mccc2 (89% identical), rabbit MCCC2 (88% identical), guinea pig MCCC2 (88% identical), rat Mccc2 (88% identical), dog MCCC2 (88% identical), tropical clawed frog mccc2 (81% identical), zebrafish mccc2 (81% identical), pig MCCC2 (79% identical), Drosophila melanogaster Mccc2 (69% identical), Caenorhabditis elegans mccc-2 (63% identical). Paralogues in human: PCCB (29% identical).
Diseases named in the same sentence as MCCC2 in open-access papers:
MCCC2 is named in the same sentence as 19 diseases in open-access papers, as found by Europe PMC text mining. Sharing a sentence is not in itself a finding about the gene and the disease. The quoted sentences say what the papers report.
prostate carcinoma (5 papers, 2011 to 2024). A carcinoma that arises from epithelial cells of the prostate gland. "Previous research has shown that MCCC2 can activate the P38 MAPK pathway to enhance aerobic glycolysis in prostate cancer." (PMID 38783226, 2024). "As a subunit of MCC, methylcrotonoyl-CoA carboxylase 2 (MCCC2) is highly expressed in breast and prostate cancers and can promote the proliferation and metastasis of tumor cells." (PMID 33407468, 2021). "In order to identify androgen-regulated genes that could possibly be used in the diagnosis/prognosis of prostate cancer, we selected from our 107-gene signature three androgen-regulated genes: MCCC2, ENDOD1 and ACSL3." (PMID 21829708, 2011). "We selected three R1881-regulated genes to be analyzed by quantitative PCR on normal prostate and prostate carcinoma samples obtained in our institute: ACSL3, MCCC2 and ENDOD1." (PMID 21829708, 2011).
colorectal cancer (2 papers, 2023 to 2024). A primary or metastatic malignant neoplasm that affects the colon or rectum. "Methylcrotonoyl‐CoA carboxylase 2 (MCCC2), a mitochondria‐related gene that catabolizes leucine during metabolism, has been shown to have different expression patterns in breast and colorectal cancers." (PMID 39491527, 2024).
hepatocellular carcinoma (2 papers, 2021 to 2025). A malignant tumor that arises from hepatocytes. "However, the role of MCCC2 and the correlation between MCCC2 and leucine in the progression of hepatocellular carcinoma (HCC) have not yet been reported." (PMID 33407468, 2021).
3-methylcrotonyl-CoA carboxylase deficiency (1 paper, 2023). 3-methylcrotonyl-CoA carboxylase deficiency (3-MCCD) is an inherited disorder of leucine metabolism characterized by a highly variable clinical picture ranging from metabolic crisis in infancy to asymptomatic adults. "Evaluation for underlying immunodeficiency was unremarkable; genetic testing revealed bi-allelic mutations in MCCC2, a known association of 3-methylcrotonyl-CoA carboxylase deficiency." (PMID 37362523, 2023).
glioma (1 paper, 2024). A benign or malignant brain and spinal cord tumor that arises from glial cells (astrocytes, oligodendrocytes, ependymal cells). "This study revealed five genes associated with the prognosis of glioma (ECI2, MCCC2, OXCT1, SUCLG2, and CPT2), providing novel insights into individualized treatment and prognosis." (PMID 39491527, 2024). "Five genes associated with the prognosis of glioma (ECI2, MCCC2, OXCT1, SUCLG2, and CPT2) were revealed and then, validated using glioma tissues, providing novel insights into individualized treatment and prognosis." (PMID 39491527, 2024). "ECI2, MCCC2, OXCT1, SUCLG2, and CPT2 were identified as prognostic genes for glioma." (PMID 39491527, 2024).
glutaric acidemia type II (1 paper, 2022). "These are the associations MCCC2—hydroxyvalerylcarnitine (3-methylcrotonylglycinuria), ETFDH—hexanoylcarnitine (glutaric acidemia type II) and SARDH—sarcosine (sarcosinemia)." (PMID 35888728, 2022).
metastatic tumor (1 paper, 2023). "We then detected the mRNA level of MCCC2 in metastatic tumor tissues, primary tumor tissues, peritumor tissues (~ 2 cm from the tumor site), and normal tissues (~ 5 cm from the tumor site) in 41 CRC patients’ samples independently." (PMID 37828426, 2023).
prostate tumors (1 paper, 2011). "Data on ACSL3, MCCC2 and ENDOD1 protein expression is available for 3 normal tissue samples and 11 prostate tumors." (PMID 21829708, 2011).
cancer (9 papers, 2011 to 2025). A tumor composed of atypical neoplastic, often pleomorphic cells that invade other tissues. "Recently, MCCC2 has been implicated as an oncogenic factor in various cancers." (PMID 37828426, 2023). "High expression of MCCC2 has been found in several cancers of prostate, colorectal, and breast origins, and has been implicated in playing important roles in tumor cell proliferation and metastasis 8-10." (PMID 40384857, 2025). "For instance, MCCC2, the host gene of circMCCC2, has been shown to be overexpressed in various cancer types, where it acts as an oncogene." (PMID 41312055, 2025). "In this study, we found an increase in mitochondrial fusion in CRC cells without MCCC2 or with less MCCC2 protein, which provides indirect evidence that MCCC2 reinforces cancer cell proliferation." (PMID 37828426, 2023). "MCCC2 was strongly up-regulated in primary cancer, although its expression in metastasis and hormonal therapy-resistant disease varies in the different databases." (PMID 21829708, 2011). "Nonetheless, the molecular basis in which MCCC2 functions in cancer progression is still unclear." (PMID 37828426, 2023). "Furthermore, several studies revealed novel signaling and regulatory functions intervened by the smaller subunit of MCC, MCCC2, in cancer cells." (PMID 35158853, 2022). "Finally, MCCC2 was up-regulated in well-differentiated tumors (P<0.005), but its expression decreased during progression to high-grade cancer (P<0.05)." (PMID 21829708, 2011). "Therefore, targeting enzymes involved in leucine metabolism, such as MCCC2, might be a potential method of treating cancer, including HCC." (PMID 33407468, 2021). "Besides abnormal uptake of leucine, the enhanced leucine metabolism pathway, such as the upregulation of MCCC2, might also be a critical method of utilizing leucine for cancer growth." (PMID 33407468, 2021). "MCCC2 and its related leucine pathway may be interesting targets for cancer therapy." (PMID 33407468, 2021). "Notably, the expression of ECI2, MCCC2, SUCLG2, and CPT2 was higher and that of OXCT1 was lower in cancer tissues than in para‐cancer tissues." (PMID 39491527, 2024). "Regrettably, it may be challenging to detect if mitochondrial fission occurs in MCCC2 overexpression CRC cells, given that mitochondria are widely distributed in cancer cells." (PMID 37828426, 2023). "Therefore, our results indicate that MCCC2 can promote ERK activation, which is a common oncogenic pathway frequently observed in cancer cells." (PMID 33407468, 2021).
tumor (3 papers, 2021 to 2024). "MCCC2 expression was significantly higher in CRC tumor tissues compared with in adjacent normal tissues, which was consistent with the TCGA cohort." (PMID 37828426, 2023). "First, by analyzing TCGA data (50 CRC cases with tumor and peritumor tissues self-matched), we found that the mRNA level of MCCC2 was significantly higher in tumor tissues than in peritumor tissues." (PMID 37828426, 2023). "The results showed that MCCC2 expression was higher in CRC tumor tissues than in peritumoral and normal tissues." (PMID 37828426, 2023). "The IHC scores were similar to the MCCC2 mRNA levels, and the IHC scores in tumor tissues were significantly higher than those in the adjacent normal tissues." (PMID 37828426, 2023). "The MCCC2 level was indeed much lower in the KD group, and tumor cell proliferation rate was also lower in the KD group revealed by Ki-67 staining and counting." (PMID 37828426, 2023). "To systematically identify the MCCC2-associated proteins, we used IP mass spectrometry to detect potential proteins that interact with MCCC2 in tumor cells." (PMID 33407468, 2021). "MCCC2 plays a significant role in cellular metabolism, energy production, and tumor development." (PMID 38783226, 2024). "The tumor samples were sectioned and subjected to IHC staining for MCCC2 and Ki-67." (PMID 37828426, 2023). "Tumor weight was significantly reduced in the MCCC2 KD mice group." (PMID 37828426, 2023). "Next, we detected the expression of tumor markers in SMMC-7721 cells after knocking down MCCC2." (PMID 33407468, 2021). "Moreover, the mRNA level of MCCC2 was the highest in metastatic tumor tissues." (PMID 37828426, 2023). "Therefore, our results demonstrate that knockdown of MCCC2 inhibits tumor growth in vivo." (PMID 33407468, 2021). "Given the extensive role of P38 MAPK signaling and MCCC2, this regulation has profound implications, extending beyond glycolysis to potentially affect other cellular processes, suggests that ECHDC2 may have a broader regulatory role in tumor cell metabolism and survival." (PMID 38783226, 2024).
MCCC2 also shares sentences with these, for which no sentence is quoted: endometriosis (1 paper); gastric cancer (1); Immunodeficiency (1); lymph node metastasis (1); neurodevelopmental disorder (1); Obesity (1); primary ciliary dyskinesia (1); Sandhoff disease (1); sarcosinemia (1).